STAT3 (signal transducer and activator of transcription 3)
Diseases named in the same sentence as STAT3 in open-access papers (continued):
Sharing a sentence is not in itself a finding about the gene and the disease.
cardiac hypertrophy (continued). "Upon MI, phosphorylated STAT3 was increased in the HSF1 KO mice, whereas inhibition of STAT3 phosphorylation ameliorated the ischaemia‐induced cardiac hypertrophy and cardiac dysfunction in mouse." (PMID 29992755, 2018). "Cardiac STAT3 phosphorylation increased in a rat model of doxorubicin-induced CKD and cardiac hypertrophy." (PMID 30424579, 2018). "In our animal model of cardiac hypertrophy, the activity and the expression level of several signal proteins were increased, including IL-6, JAK and p-STAT3." (PMID 29433438, 2018). "Despite the induction of cardiac hypertrophy by activation of JAK/STAT signaling, STAT3 plays a key role in cardio-protection in response to numerous stress situations including pressure overload." (PMID 23270329, 2012). "STAT3 and MAPK (ERK)s pathway were induced by IL-6 receptor signaling systems and contributed to the cardiac hypertrophy." (PMID 21785627, 2011). "Interestingly, this study demonstrates a previously unannotated functional link between STAT3 and CARM1 in the pathogenesis of pathological myocardial hypertrophy." (PMID 40192103, 2025). "The activation of the JAK2/STAT3 signaling pathway was detected in hypertrophic hearts elicited by isoproterenol and the inhibition of the activities of JAK2 and STAT3 mitigated myocardial hypertrophy." (PMID 40271123, 2025). "Notably, murine studies have elucidated that the OSMR knockout exacerbates pressure overload-induced cardiac hypertrophy by influencing macrophages and the OSM/LIFR/STAT3 signaling pathway." (PMID 39411310, 2024). "Additionally, previous research has indicated that Hsp90 plays a pivotal role in modulating ventricular hypertrophy by activating the MAPK pathway, NF-κB pathway, STAT-3 pathway, and stabilizing HIF-1 alpha." (PMID 39850481, 2024). "Based on the in vivo and in vitro data, we concluded that OSMR deficiency could contribute to the development of pressure overload-induced cardiac hypertrophy by modulating macrophage function and the OSM/LIFR/STAT3 signalling pathway." (PMID 37120549, 2023). "We thus asked whether OSM/LIFR/STAT3 signalling was activated in macrophages and whether it participated in OSMR deletion-regulated cardiac hypertrophy." (PMID 37120549, 2023). "In addition, IL-6, which is produced by cardiomyocytes in response to hypertrophic stimuli, activates the STAT3 and MAPK signaling pathway in myocardial hypertrophy." (PMID 38158445, 2023). "Mechanistically, miRNA-148a, that was selectively encapsulated into CDCs-exosomes mediated the therapeutic effect of HHP-EXO to myocardial hypertrophy via down-regulation of the expression of GP130, leading to inhibition of STAT3, ERK1/2 and AKT signaling pathways." (PMID 36195937, 2022). "Hirudin can be highly bound to STAT3, IL-6, and MAPK1 and found by molecular docking, which may be the basis for its inhibitory effect on myocardial hypertrophy." (PMID 35784743, 2022). "STAT3 and NFAT2 play key roles in the development of cardiac hypertrophy." (PMID 36686707, 2022). "(P < 0.05) These results suggested that overexpression of miR-320 might heighten TGF-β, IL-6, p-STAT3 and suppress PTEN in cardiac hypertrophy and fibrosis." (PMID 34582362, 2021). "We found that down-regulated PTEN was reversed by orexin B, and the enhanced type I and type III collagen, TGF-β, IL6, p-STAT3, STAT3 were also reversed by orexin B, suggesting PTEN was involved in the overexpression of miR-320-induced cardiac hypertrophy and fibrosis in vitro." (PMID 34582362, 2021). "MiR-320 mimics accelerated cardiac hypertrophy and cardiac fibrosis via the IL6/STAT3/PTEN axis." (PMID 34582362, 2021). "Administration of magnolol and TG-101348 or JSI-124 (both JAK2 selective inhibitors) could prevent myocardial hypertrophy and fibrosis, accompanied by the decrease in the phosphorylation level of JAK2 and STAT3." (PMID 34764873, 2021).
cardiac hypertrophy (continued). "Similarly, in myocardial hypertrophy, PARP1 upregulated STAT3 transcriptional activity by retaining phosphorylated-STAT3 in the nucleus independently of JAK2 activation." (PMID 32900001, 2020). "Taken together, these findings suggested that cardiomyocyte-specific STAT3 ablation made mice developed cardiac hypertrophy without affecting blood pressure." (PMID 33365331, 2020). "Swimming reduced cardiac STAT3 phosphorylation both in the control and CKD group, which might lead to the attenuation of cardiac hypertrophy in CKD animals." (PMID 30424579, 2018). "Although alteration of cardiac STAT3 has been reported in CKD, whether this is due to direct effects or due to secondary effects via cardiovascular complications of CKD (e.g., cardiac hypertrophy and fibrosis) is very difficult to distinguish." (PMID 30424579, 2018). "Recent gene deletion studies suggest that STAT3 at endogenous levels does not couple to cardiac hypertrophy." (PMID 30619368, 2018). "It has been shown that EA could attenuate the elevated blood pressure and be of benefit in restoring cardiac hypertrophy in SHR by enhancing NO/NOS activity and reducing the level of IL-6, STAT3, BNP, and so on." (PMID 28293268, 2017). "In Stat3-silenced cardiomyocytes, the PGE2-mediated protein synthesis was dramatically inhibited, suggesting that activation of Stat3 works downstream of PGE2-EP4-ERK1/2-mediated cardiac hypertrophy in vitro." (PMID 27190998, 2016). "Increased Glc oxidation in the face of unaltered FAO is further evidence that mitochondrial metabolic function is not adversely affected by STAT3 deletion in the heart under the chronic stress condition of cardiac hypertrophy." (PMID 27899891, 2016). "Our study also reveals that cardiac myocyte expression of STAT3 is not important for the development of cardiac hypertrophy in response to ANG II-induced hypertension." (PMID 27899891, 2016). "Paradoxically, the accumulation of unphosphorylated STAT3 (U-STAT3) in the nucleus has been suggested to drive pathological cardiac hypertrophy and inflammation via non-canonical gene expression, perhaps involving a distinct acetylation profile." (PMID 26664907, 2015). "Therefore, we hypothesize that STAT3 serves as a substrate of YOD1 in cardiomyocytes and mediates YOD1’s role in cardiac hypertrophy." (PMID 40561034, 2025). "In addition, Ang II can induce Toll-like receptor phosphorylation of STAT3, increase IL-6 production, and continuously activate the JAK/STAT pathway, thereby providing positive feedback and promoting myocardial hypertrophy, fibrosis, and ventricular remodeling." (PMID 38495094, 2024). "In vivo, PM reversed TAC‐induced cardiac hypertrophy, as determined by down‐regulating ratios of heart weight to body weight (HW/BW), heart weight to tibial length (HW/TL) and expressions of hypertrophy‐related proteins accompanied by the inhibition of the JAK2/STAT3 pathway." (PMID 35365949, 2022). "As shown in the results above, Ang II can promote the expression of p-ERK, p-STAT3, and NFAT2, while Farrerol and ERK inhibitors can significantly inhibit their expression, and we found that Farrerol may exert an anti-cardiac hypertrophy effect through MAPK/ERK." (PMID 36686707, 2022). "Therefore, we used WP1066 (Beyotime, China), a specific inhibitor of STAT3 phosphorylation, and FR180204 (Beyotime, China), a specific inhibitor of ERK phosphorylation, to provide evidence that rhein inhibits the myocardial hypertrophy cell phenotype by targeting p-STAT3 and P-ERK." (PMID 36091816, 2022). "However, we did not use a STAT3 or ERK inhibitor to examine the effect on cardiac hypertrophy and the expression of downstream prohypertrophic inflammatory cytokines." (PMID 29358851, 2017). "Therefore, our findings suggest that the direct non-genomic actions of STAT3 at the level of the mitochondria do not play a role in the development of heart failure in response to increased cardiac hypertrophy." (PMID 27899891, 2016).
cardiac hypertrophy (continued). "In addition, acute pressure overload and mechanical stress can activate JAK1, JAK2, TYK2, STAT2, STAT3, and the IL-6 family (including cardiotrophin 1, LIF, and IL-6 itself), and it has been suggested that this activation is a potentially important mechanism of myocardial hypertrophy." (PMID 36671504, 2023). "For a number of reasons the findings arguing against a role for STAT3 in cardiac hypertrophy that are based on its targeted KO in cardiomyocytes may not be definitive, and intriguing reports persists suggesting that STAT3 does play a more active role depending upon the circumstances." (PMID 30619368, 2018). "CTS treatment could no longer protect against pressure overload-induced mouse cardiac hypertrophy and fibrosis after AAV9-mediated STAT3 overexpression." (PMID 36743695, 2023). "Although our results might not exclude other mechanisms by which HSF1 suppresses cardiac hypertrophy induced by ischaemia, the inhibitory effect of HSF1 on the development of cardiac hypertrophy seems to be largely dependent on the repression of JAK2/STAT3 by HSF1." (PMID 29992755, 2018).
Autoimmunity (128 papers, 2010 to 2026). The occurrence of an immune reaction against the organism's own cells or tissues. "In contrast, gain‐of‐function variants (GOF), commonly in the SH2 domain, enhance STAT3 dimerization and signalling, resulting in immune dysregulation, autoimmunity and lymphoproliferation." (PMID 41527523, 2026). "GOF mutations in STAT3 lead to excessive activation of STAT3 signaling, promoting hyperinflammation and severe autoimmunity." (PMID 41438753, 2025). "Autosomal dominant gain-of-function (GOF) variants in the signal transducer and activator of transcription 3 (STAT3) result in an inborn error of immunity characterized by multi-organ autoimmunity and lymphoproliferation." (PMID 40703313, 2025). "Previous studies have shown that STAT3 variants from patients with early‐onset multiorgan autoimmunity are mostly mapped to the DNA‐binding domain." (PMID 38404237, 2024). "Germline gain‐of‐function (GOF) variants in the signal transducer and activator of transcription 3 (STAT3) gene lead to a rare inherited disorder characterized by early‐onset multiorgan autoimmunity." (PMID 38404237, 2024). "Early‐onset diabetes is the most frequent endocrine manifestation of multiorgan autoimmunity caused by STAT3 GOF variants." (PMID 38404237, 2024). "In the STAT3 gene, GoF variants lead to its hyperactivation, causing immune dysregulation, early-onset lymphoproliferation and autoimmunity whereas LoF variants result in impaired STAT3 function, leading to a hyper-IgE recurrent infection syndrome-1 (HIES1)." (PMID 38659694, 2024). "In summary, we describe a patient with infantile‐onset diabetes and multiorgan autoimmunity caused by a novel germline GOF variant (c.1069A>G) in STAT3." (PMID 38404237, 2024). "In the present study, the patient displayed prominent features of early‐onset multiorgan autoimmunity cased by STAT3 GOF variants, including infantile‐onset endocrinopathies, enteropathy, and postnatal short stature." (PMID 38404237, 2024). "In contrast, germline STAT3 GOF mutations lead to an early-onset disease of poly-autoimmunity and lymphoproliferation and are found in all functional domains of the protein." (PMID 37702894, 2023). "A pathogenic STAT3 variant with several previous reports of autoimmunity and immunodeficiency was detected from a patient (Case 4) with recurrent infection history, lymph node enlargement, pancytopenia, and splenomegaly." (PMID 37325673, 2023). "B cell-specific deletion of STAT3 causes severe autoimmunity in mice, so we can infer potential anti-tumor benefits from targeting STAT3 signaling in B cells." (PMID 35406557, 2022). "STAT3 gain-of-function mutations manifest with a variety of clinical symptoms including lymphoproliferation, and multiorgan autoimmunity." (PMID 35603189, 2022). "STAT3 is vital for vertebrate development while its mutations are associated with immunodeficiency, autoimmunity and cancer." (PMID 35725413, 2022). "Activating germline mutations of STAT3 result in early-onset lymphoproliferation, immune deficiency and multi-organ autoimmunity." (PMID 36441748, 2022). "STAT3 has also been implicated in Teff resistance and the reversal of the resistant phenotype in autoimmunity with STAT3 inhibitors." (PMID 36282595, 2022). "STAT3 GOF mutations lead to an increased transcriptional activity that causes autoimmunity and lymphoproliferation." (PMID 34207510, 2021). "STAT3 GOF mutations were identified by next gene sequencing in those with early-onset multi-organ autoimmunity." (PMID 33731004, 2021). "Some publications demonstrated that STAT3 SNPs appeared to be associated with cancers, autoimmunity or selected infections." (PMID 34307193, 2021). "It has been reported that STAT3 SNP were significantly associated with cancers, immunodeficiency, autoimmunity and viral hepatitis." (PMID 34307193, 2021). "STAT3 GOF mutations were identified by gene sequencing in those with early-onset multi-organ autoimmunity." (PMID 33731004, 2021).
Autoimmunity (continued). "In this manuscript, we focus on heterozygous germline activating mutations in STAT 3 (STAT3 GOF) as a cause of a syndrome of early onset autoimmunity and lymphoproliferation with highly variable penetrance." (PMID 31799221, 2019). "In line with this, STAT3 gain-of-function mutations can cause early-onset lymphoproliferation and autoimmunity and have been associated with Th17 hyperactivation." (PMID 31569642, 2019). "One mechanism through which STAT3 is thought to lead to autoimmunity is by promoting the activation and expansion of autoimmunity-associated TH17 cells." (PMID 31921101, 2019). "Patients with STAT3 GOF mutations show massive multiorgan autoimmunity, autoimmune cytopenia, lymphoproliferation, and immunodeficiency, likely due to impaired Treg differentiation and functions." (PMID 30061896, 2018). "More recently, gain-of-function (GOF) mutations in STAT3 were also identified, this time in patients who presented with early onset autoimmunity as well as immunodeficiency." (PMID 29472924, 2018). "This contention is supported indirectly by the observation of the paradoxical coincidence of antibody deficiency and autoimmunity observed with some forms of primary immune deficiency, including STAT3 GoF32,34." (PMID 29476109, 2018). "Remarkably, germline STAT3-activating mutations have been detected in rare patients developing multi-organ autoimmunity, confirming a key role for this factor in autoimmunity." (PMID 29316631, 2018). "In support of this concept, autoimmunity, hypogammaglobulinemia, lymphoproliferation, and mycobacterial disease were demonstrated in patients with activating mutations in STAT3." (PMID 29056905, 2017). "When remission was reached through medical intervention, IL-17 levels normalized and the clinical symptoms improved, supporting the idea that STAT3 gain-of-function mutations can cause hyperactivation of the Th17 pathway and thereby contribute to autoimmunity." (PMID 26343524, 2015). "Forced expression of EGR2 in naïve T cells converts them into LAG3 expressing and IL-10 secreting regulatory cells while EGR2 deficiency results in lupus-like autoimmunity, as well as increased STAT3 phosphorylation and IL-17 secretion." (PMID 25880134, 2015). "In contrast to deficiency, persistent activity of STAT3 plays a causative role in the development of life-threatening diseases that include cancer and autoimmunity." (PMID 21625522, 2011). "Conversely, GOF mutations in STAT3 lead to early-onset autoimmunity and lymphoproliferation." (PMID 41438753, 2025). "There are links between STAT3 gain-of-function mutations and early-onset autoimmunity." (PMID 40636934, 2025). "Similarly, the STAT3 P471R variant hyperactivates the T helper 17 (Th17) pathway, increasing IL-17 production and triggering autoimmunity." (PMID 40831950, 2025). "Gain‐of‐function (GOF) variants of STAT3 cause early‐onset multiorgan autoimmunity." (PMID 38404237, 2024). "However, SLE have also been observed in patients with STAT3 loss of function mutation, suggesting the multiple and distinct biological roles of STAT3 in autoimmunity." (PMID 40625455, 2024). "STAT3 mutations are therefore predisposed to autoimmunity via overactivation." (PMID 37140667, 2023). "A far-sighted and open-minded research attitude is of great benefit if unexpected results (such as SLE-like autoimmunity in STAT3 DN mutations) can be assigned to these diseases and new explanatory approaches for a holistic understanding of the syndromes arise." (PMID 37140667, 2023). "This insight into the mechanism by which manipulation of STAT3 affects the SE activity and its associated gene expression in B cells may have implications for future drug development in autoimmunity." (PMID 35188103, 2022).